INS (insulin)
Diseases named in the same sentence as INS in open-access papers (continued):
Sharing a sentence is not in itself a finding about the gene and the disease.
Insulin resistance (continued). "Low plasma IGF-1 is associated with reduced insulin sensitivity and increased insulin resistance, which had been showed in clinical studies." (PMID 27343122, 2016). "The abnormal state of insulin (hyperinsulinemia or insulin resistance) is one cause, and it promotes cancer growth and progression through its effects on the insulin and insulin-like growth factor pathways." (PMID 28003023, 2016). "The G-allele of both SNPs significantly decreased insulin resistance and increased insulin secretion." (PMID 27465520, 2016). "The liver is one of the major organs that are targeted by insulin and implicated in insulin resistance, and it expresses PACAP receptors." (PMID 28044141, 2016). "It is associated with insulin resistance, impaired insulin signaling, β-cell dysfunction, abnormal glucose levels, altered lipid metabolism, sub-clinical inflammation and increased oxidative stress." (PMID 27213445, 2016). "Type 2 diabetes mellitus (T2DM) is a progressive disease, characterized by insulin resistance and ongoing loss of endogenous insulin secretion." (PMID 27115999, 2016). "Adipose tissue expression of sFRP2 has been associated with insulin resistance, and this study defined serum sFRP2 as an adipokine strongly associated with abnormal glucose tolerance and increased insulin secretion." (PMID 27685706, 2016). "Ando et al20 showed that insulin and insulin resistance are correlated with an increase in the risk of self-reported kidney stones." (PMID 26616396, 2016). "High‐glucose culture conditions of differentiating 3 T3‐L1s, associated with insulin resistance, was found to reduce protein levels of molecular markers of the insulin‐signalling pathway, including PI3Kinase and phospho‐AKT as well as PIP3 levels." (PMID 26467985, 2016). "Insulin and glucose are typically measured in a fasting state, with fasting increased levels relatively specific and sensitive markers of insulin resistance and a hallmark phenotype of Type 2 diabetes." (PMID 27530235, 2016). "Contrary to this, in humans, overnight infusion of hydrocortisone (0.2 mg/kg/h intravenously) causes increased insulin sensitivity in subcutaneous adipose tissue, despite peripheral insulin resistance." (PMID 27527232, 2016). "Insulin resistance refers to the deficient regulation by insulin of energy substrate utilisation in peripheral tissues." (PMID 27073920, 2016). "Adiponectin is a sensor of insulin and can induce body weight loss and insulin resistance, with high levels of tumor necrosis factor (TNF) in plasma and adipose tissue." (PMID 27547756, 2016). "Since this elevated blood glucose and reduced glucose clearance is associated with insulin resistance we measured day and night circulating insulin levels." (PMID 27040510, 2016). "BMI had the highest, statistically significant positive correlation with fasting insulin (r = 0.51, p < 0.0001) and HOMA-IR (r = 0.48, p < 0.0001), indicating that higher BMI was associated with higher fasting insulin and insulin resistance." (PMID 27824069, 2016). "Pancreatic β-cell dysfunction and reduced insulin output in the presence of insulin resistance is the primary cause of T2D." (PMID 27195491, 2016). "Insulin resistance (characterized by higher serum insulin levels) is strongly linked to abdominal and visceral obesity, and adipose tissue is known to release adipokines, including leptin and adiponectin, into the systemic circulation." (PMID 27242922, 2016). "T2DM, which is defined as hyperglycemia of sufficient magnitude to cause detrimental effects, results when insulin resistance develops and is followed by dysregulation of insulin secretory responses, with loss of beta-cell mass." (PMID 26959059, 2016). "T2DM is a metabolic disease with varying degrees of insulin resistance and impaired insulin secretion from pancreatic islet beta cells, which causes hyperglycemia or high blood glucose." (PMID 27376154, 2016).
Insulin resistance (continued). "The elevated plasma TG is associated with insulin resistance and increased insulin secretion of β-cells." (PMID 27034649, 2016). "Normal pregnancy is characterized by a progressive increase in insulin resistance, associated with β-cell hyperplasia and a large increase in insulin secretion, that leads to a transient state of glucose intolerance." (PMID 27559358, 2016). "This is due to the plasma glucose and insulin levels being higher in the insulin-resistant case, which counteracts the reductions in uptake and release rates caused by the insulin resistance, and leads to similar fluxes." (PMID 27306890, 2016). "STZ not only causes glucose metabolism disorders but it also induces insulin resistance, which results in an increase of the blood insulin level." (PMID 27257845, 2016). "Skeletal muscle of F13a1−/− mice also showed improved insulin sensitivity, and studies have shown that insulin resistance in muscle was associated with the increased hydroxyproline content in type 2 diabetic patients." (PMID 27759118, 2016). "While these data describe the contribution of muscle to inactivity-induced insulin resistance, the underlying mechanisms driving the changes in insulin and glucose have only been partly uncovered." (PMID 27376322, 2016). "Previous studies indicated that inhibition of ceramide synthesis, including ceramide-1-phosphate and glucosylceramide, inhibited several underlying causes of insulin resistance and improved insulin sensitivity in tissues." (PMID 27629750, 2016). "Abnormally increased skeletal-muscle-specific E3 ubiquitin ligase (MG53) is associated with the inhibition of insulin signalling and insulin resistance (IR) in animal models." (PMID 28443211, 2016). "FFAs also cause hepatic insulin resistance by inhibiting insulin-mediated suppression of glycogenolysis." (PMID 27478435, 2016). "A higher percentage of the Orang Asli showed high insulin levels and hsCRP compared to the healthy Malays denoting possible risk of insulin resistance." (PMID 27009064, 2016). "T2DM is a metabolic disease characterized by hyperglycemia, resulting from a progressive loss of insulin secretion on the background of insulin resistance." (PMID 27782064, 2016). "In these conditions, the appearance of insulin resistance is frequently associated with a diminished capacity of tissues or cells to respond to levels of insulin." (PMID 27478531, 2016). "The associations between sleep and fasting insulin levels and insulin resistance remained significant even after adjustment for BMI and other confounders." (PMID 27870902, 2016). "In this study, however, insulin resistance seemed to be less involved in the inverse association between serum TC level and insulin secretion presumably because subjects were much younger (mean age: 43) than those in our study." (PMID 26881755, 2016). "Subcutaneous white adipose tissue (scWAT) is associated with an insulin sensitive phenotype, whereas visceral white adipose tissue (vWAT) is associated with obesity, type II diabetes, dyslipidemia and insulin resistance." (PMID 28025491, 2016). "Many lines of evidence support the benefits of myo-Ins supplementation for some metabolic disorders associated with insulin resistance, because of its insulin mimetic properties." (PMID 27725832, 2016). "It is associated with insulin resistance (IR), impaired insulin signaling, β-cell dysfunction, abnormal glucose levels and altered lipid metabolism." (PMID 27213445, 2016). "Growing evidence also suggests that low serum Vitamin D is associated with insulin resistance and Type II diabetes and that appropriate Vitamin D supplementation can improve insulin sensitivity." (PMID 27314342, 2016). "Type B insulin resistance is a rare autoimmune disease characterized by the presence of anti-insulin receptor antibodies, which impair the binding of insulin to its receptor and cause severe insulin resistance (IR)." (PMID 27142369, 2016).
Insulin resistance (continued). "This study aimed to test the associations between cotinine and measures of insulin resistance or insulin secretion." (PMID 27992538, 2016). "Resistin is a cysteine-rich polypeptide, which antagonizes insulin effect and causes insulin resistance." (PMID 27193069, 2016). "A hallmark of obesity‐driven T2D is insulin resistance, and thus, much effort is placed into treatments that promote “insulin sensitisation”." (PMID 27137487, 2016). "A hallmark of obesity‐driven T2D is insulin resistance, and thus “insulin sensitisation” has been an attractive strategy for treatment." (PMID 27137487, 2016). "Further, PTX3 was positively correlated with insulin sensitivity and negatively correlated with insulin resistance, although these associations were modest." (PMID 26842615, 2016). "As an indicator of cardiorespiratory fitness, physical fitness score demonstrated a weak negative correlation, indicating that a lower physical fitness score was associated with higher fasting insulin and insulin resistance." (PMID 27824069, 2016). "After 12 months of a low-fat intervention, subjects who are homozygous for the major allele (TT) display lower plasma insulin concentrations, lower insulin resistance and higher insulin sensitivity compared with carriers of the minor allele C (TC + CC)." (PMID 26977390, 2016). "The abnormal glucose regulation in the GK rat develops in association both with impaired insulin secretion and with insulin resistance as reviewed by Östenson and Movassat." (PMID 27496100, 2016). "Obesity in children is associated with leptin and insulin resistance, manifested by reduced serum levels of ghrelin and increased leptin and insulin levels." (PMID 26757831, 2016). "Fasting insulin and the homeostasis model assessment of insulin resistance was negatively associated with RR, SDNN, and RMSSD, and the association was stronger among men compared with women." (PMID 26983644, 2016). "Whole body insulin resistance in Adicer KO mice was associated with reduced insulin signaling in WAT as measured by Akt and Erk1/2 phosphorylation." (PMID 27241713, 2016). "Gender was significant covariate interacting with insulin sensitivity/insulin resistance and obesity indexes associations in this population." (PMID 27189377, 2016). "A study published in 2015 of a population-based sample found that TAC/d was more strongly associated with multiple insulin resistance–related risk factors — fasting blood glucose, fasting insulin, and C-peptide — than was bouted MVPA." (PMID 27763832, 2016). "M1 macrophages, which represent a pro-inflammatory state, can secrete inflammatory cytokines such as tumor necrosis factor (TNF)-α, interleukin-6 (IL-6) and IL-1β that interfere with insulin signaling, and cause adipocyte dysfunction and insulin resistance." (PMID 27878229, 2016). "Vitamin D deficiency can play a role in insulin resistance and the pathogenesis of type 2 diabetes, through effects on both β-cell function and insulin sensitivity." (PMID 27413370, 2016). "Altered expression or signaling of the insulin signal transduction pathway is a common occurrence associated with insulin resistance." (PMID 27738449, 2016). "Many of the loci that have been identified as being associated with risk of developing insulin resistance harbour genes nearby that are good biological candidates for association with measures of insulin sensitivity." (PMID 27312935, 2016). "There are some reports on the association between insulin resistance and muscle mass, but few studies have examined the association between insulin secretion and muscle mass." (PMID 27612202, 2016). "Long-term treatment of adipocytes with IL-6, IL-1β, or TNFα was shown to inhibit insulin signaling and cause insulin resistance." (PMID 27066503, 2016). "In exploratory factor analysis, five underlying factors, namely insulin resistance, aging, sex differences, insulin secretion, and glycemic control, represented patient characteristics." (PMID 26849676, 2016).
Insulin resistance (continued). "Vitamin D deficiency has been linked to insulin resistance, and an improvement of insulin action has been observed after vitamin D supplementation." (PMID 26833056, 2016). "This project will test the novel concept that a high‐palmitate diet disrupts caveolae function and thus contributes to impaired insulin signaling and insulin resistance through loss of IR regulation by CAV3." (PMID 27033451, 2016). "The beneficial effects of creosote bush ethanolic extract in the HFD hamster model were a reduction of insulin resistance, associated with lower serum insulin and leptin, lower hepatic lipid peroxidation and higher liver antioxidant capacity." (PMID 27445827, 2016). "In the adipose tissue, the pro-inflammatory response causes insulin resistance, whereas the anti-inflammatory response preserves insulin sensitivity." (PMID 27148161, 2016). "Decreased TT levels in men are associated with insulin resistance and reduced insulin sensitivity and have been found to predict insulin resistance, obesity, and T2DM." (PMID 27274996, 2016). "More specifically, adipose tissue hypoxia, which develops with the onset of obesity, has been linked to the development of insulin resistance and type 2 diabetes by decreasing insulin signaling pathways." (PMID 26881257, 2016). "The first is that when the skeletal muscle is insulin resistant, the liver is overloaded, and over time, this causes the liver to stop functioning normally and develop insulin resistance." (PMID 27306890, 2016). "While levels tended to drop at 1 h in controls, they increased in the MetS group suggesting impaired suppression of plasma NEFA by feeding despite the associated increase in insulin and consistent with systemic insulin resistance." (PMID 26727015, 2016). "After the pancreatic beta cells function declines and an insufficient secretion of insulin appears, a transition will be caused from the stage of insulin resistance to impaired glucose tolerance, followed by T2DM." (PMID 27974926, 2016). "The pathophysiology of stress induced hyperglycemia is thought to reflect temporary insulin resistance coupled with relative insulin deficiency, in that plasma insulin concentrations are inadequate to compensate for hyperglycemia." (PMID 27824898, 2016). "Activation of the NF-κB signaling pathway (which is closely correlated with inflammation) has been implicated in the pathogenesis of impaired insulin secretion, insulin resistance, and diabetic vascular complications in T2DM." (PMID 27589775, 2016). "Conversely, L cells are responsive to insulin and insulin resistance is associated with impaired GLP-1 secretion in vitro and in vivo." (PMID 27148273, 2016). "In the estrogen deficient state, glucose metabolism is deteriorated by increased insulin resistance and menopausal women with low insulin secretion capacity are susceptible to type 2 diabetes." (PMID 27216600, 2016). "This is consistent with a role of obesity-related insulin- resistance in causing hyperandrogenemia in these girls through an effect of insulin on adrenal and ovarian steroidogenesis, manifesting as early adrenarche and subsequent PCOS." (PMID 27423183, 2016). "Insulin resistance in a number of peripheral tissues and an inadequate β‐cell response despite normal or even increased amounts of circulating insulin have been implicated in progressive type 2 diabetic complications and metabolic syndrome." (PMID 27095835, 2016). "In the Fenland study, both higher BMI and higher fasting insulin level, a measure of fasting-state insulin resistance, were associated with higher levels of BCAAs." (PMID 27898682, 2016). "Type 1 diabetes is caused by autoimmune destruction of insulin-producing β-cells in pancreatic islets of Langerhans, while type 2 diabetes frequently occurs in older individuals with systemic insulin resistance and reduced insulin production." (PMID 27662374, 2016).
Insulin resistance (continued). "Insulin resistance, defined as impaired responsiveness of the body to insulin, is a prediabetic stage associated with obesity, leading to type 2 diabetes." (PMID 27071614, 2016). "Ectopic lipid accumulation in insulin-responsive tissues such as skeletal muscle and liver is associated with insulin resistance, type 2 diabetes, and adverse metabolic phenotypes." (PMID 27313625, 2016). "Elucidating the mechanisms underlying the insulin-sensitizing actions of adiponectin will provide a guide to our understanding and treatment of insulin resistance." (PMID 26993044, 2016). "Systemic insulin resistance triggers chronic hyperglycaemia, which causes pancreatic β cells to secrete more insulin." (PMID 27795741, 2016). "The vast majority of the loci related to T2D are primarily associated with insulin secretion and β-cell function with far fewer variants apparently influencing insulin resistance." (PMID 27312935, 2016). "More interestingly, apocynin also decreased these parameters in liver, corroborating the findings of improved insulin sensitivity, as the augmented levels of these markers in the liver are associated with insulin resistance." (PMID 27057272, 2016). "Early alterations in insulin and cortisol hormones influencing glucose homeostasis increase the risk of developing insulin resistance and obesity later in life." (PMID 27087404, 2016). "These loci have been used in two further studies to generate an insulin resistance genetic risk score to examine the relationship between variants associated with fasting insulin and an individual’s risk of developing insulin resistance and T2D [25•, 26•]." (PMID 27312935, 2016). "Impaired insulin action in peripheral organs results in a loss of sensitivity to insulin, which is also called insulin resistance." (PMID 27098727, 2016). "This same study and some studies utilizing hexokinase- and phosphofructokinase-deficient mice demonstrate development of insulin resistance, glucose intolerance, and elevated blood insulin with disruption of glycolytic flux." (PMID 27486508, 2016). "Association between serum cortisol levels and insulin resistance/secretion assessed by homeostasis model assessment using fasting blood glucose and insulin levels (HOMA-R and HOMA-ß, respectively) were examined." (PMID 27861636, 2016). "Studies in rodents and humans showed that higher PTP1B expression in peripheral tissues was associated with an attenuation of insulin signalling, which contributed to insulin resistance." (PMID 27479001, 2016). "Insulin resistance or impaired insulin signaling is a main cause for malfunctioned glucose metabolism and plays a pivotal role for the pathogenesis of T2DM4." (PMID 27145908, 2016). "Postprandial insulin levels are diagnostic markers to show insulin resistance and a predictive risk factor for cardiovascular risk." (PMID 27803937, 2016). "Skeletal muscle insulin resistance, a primary feature of Type 2 diabetes, is caused by a decreased ability of muscle to respond to circulating insulin." (PMID 28248217, 2016). "Our results demonstrate that downregulation of uterine IDE protein expression in hCG-treated and insulin+hCG-treated rats is associated with the onset of insulin resistance and/or hyperandrogenism." (PMID 27461373, 2016). "Given the opposite directions of association seen between insulin resistance and insulin secretion and between insulin resistance and insulin clearance, the inverse relationship of HOMA-%B and MCRI in our study was expected." (PMID 27846285, 2016). "All eight components included in the calculation of the FINDRISC were associated more strongly with insulin resistance than with impaired insulin secretion." (PMID 27851812, 2016). "We have shown that brain insulin resistance affects very specifically the interaction of the hypothalamus with frontal areas and is associated with insulin sensitivity and amount of visceral fat." (PMID 27344314, 2016).